LPIN1 (lipin 1)
Description:
Acts as a magnesium-dependent phosphatidate phosphatase enzyme which catalyzes the conversion of phosphatidic acid to diacylglycerol during triglyceride, phosphatidylcholine and phosphatidylethanolamine biosynthesis and therefore controls the metabolism of fatty acids at different levels. Is involved in adipocyte differentiation (By similarity). Recruited at the mitochondrion outer membrane and is involved in mitochondrial fission by converting phosphatidic acid to diacylglycerol (By similarity). Acts also as nuclear transcriptional coactivator for PPARGC1A/PPARA regulatory pathway to modulate lipid metabolism gene expression (By similarity).
Synonyms: KIAA0188; PAP1
Tractability: Antibody: the Human Protein Atlas places it where antibodies can reach. PROTAC: UniProt records ubiquitination sites on it; ubiquitination databases record sites on it.
Gene: Protein-coding gene on chromosome 2 (11,677,544 to 11,827,409, forward strand). Ensembl gene ENSG00000134324.
Subcellular location: Cytoplasm, cytosol; Endoplasmic reticulum membrane; Nucleus membrane
Subcellular location (Human Protein Atlas): Cytosol; Plasma membrane
Pathways (Reactome):
Metabolism: Synthesis of PC; Synthesis of PE; Triglyceride biosynthesis
Cell Cycle: Depolymerization of the Nuclear Lamina
Gene expression (Transcription): MLL4 and MLL3 complexes regulate expression of PPARG target genes in adipogenesis and hepatic steatosis
Gene Ontology:
Molecular function: phosphatidate phosphatase activity; protein binding; transcription coactivator activity
Biological process: phosphatidylethanolamine metabolic process; triglyceride biosynthetic process; cellular response to insulin stimulus; fatty acid catabolic process; mitotic nuclear membrane disassembly; positive regulation of cold-induced thermogenesis; positive regulation of transcription by RNA polymerase II; triglyceride mobilization; animal organ regeneration; negative regulation of myelination; negative regulation of phosphatidic acid biosynthetic process
Cellular component: cytosol; endoplasmic reticulum; endoplasmic reticulum membrane; cytoplasm; mitochondrial outer membrane; nuclear envelope; nuclear membrane; nucleoplasm; nucleus
Genetic constraint (gnomAD): Loss-of-function variants: 57 observed, 90.6 expected, observed/expected ratio (o/e) 0.63, 90% interval 0.51 to 0.78. The upper end of that interval is the gene's LOEUF score, 0.78, which puts it in group 3 of 6, group 1 being the genes least tolerant of losing a copy. Missense variants: 959 observed, 1,100.8 expected, observed/expected ratio (o/e) 0.87, 90% interval 0.82 to 0.92. Synonymous variants: 410 observed, 434.93 expected, observed/expected ratio (o/e) 0.94, 90% interval 0.87 to 1.02.
Gene-disease validity (ClinGen):
ClinGen rates the evidence that LPIN1 causes each of these diseases.
myoglobinuria, acute recurrent, autosomal recessive (autosomal recessive): Definitive.
Homologues: Orthologues: chimpanzee LPIN1 (99% identical), macaque LPIN1 (98% identical), dog LPIN1 (90% identical), rabbit LPIN1 (89% identical), mouse Lpin1 (89% identical), rat Lpin1 (89% identical), pig LPIN1 (87% identical), guinea pig LPIN1 (83% identical), tropical clawed frog lpin1 (71% identical), zebrafish lpin1a (62% identical), zebrafish lpin1b (55% identical), Drosophila melanogaster Lpin (36% identical), and 1 more. Paralogues in human: LPIN2 (49% identical), LPIN3 (45% identical), AP5Z1 (13% identical).
Diseases named in the same sentence as LPIN1 in open-access papers:
LPIN1 is named in the same sentence as 115 diseases in open-access papers, as found by Europe PMC text mining. Sharing a sentence is not in itself a finding about the gene and the disease. The quoted sentences say what the papers report.
Insulin resistance (28 papers, 2008 to 2025). Increased resistance towards insulin, that is, diminished effectiveness of insulin in reducing blood glucose levels. "One of our most striking observations was the phenotype of increased hepatic insulin resistance and lipid accumulation and the demonstration that loss of adipocyte Lpin1 is sufficient to drive liver injury in mice fed a MASH-inducing diet." (PMID 39405118, 2024). "The critical roles that the phosphatase cascade plays in humans and mice are typified by assorted abnormalities (e.g., lipodystrophy, insulin resistance, peripheral neuropathy, rhabdomyolysis) that result from loss of lipin 1 PA phosphatase activity." (PMID 38141768, 2024). "Clamp studies also demonstrated that Adn-Lpin1–/– mice exhibited reduced glucose uptake into skeletal muscle and BAT, suggesting that loss of lipin 1 in adipose tissue leads to multi-tissue insulin resistance." (PMID 39405118, 2024). "To identify the molecular pathways associated with insulin resistance and steatosis in Adn-Lpin1–/– mice, we performed bulk RNA sequencing in the liver." (PMID 39405118, 2024). "The critical roles that PAP activity plays in humans and mice are typified by assorted abnormalities (e.g., lipodystrophy, insulin resistance, peripheral neuropathy, rhabdomyolysis) that result from the loss of the lipin 1 enzyme." (PMID 39009344, 2024). "Mice with spontaneous mutations, including the fatty liver dystrophy (fld) gene that was later identified as the Lpin1 gene, exhibit loss of body fat, fatty liver, hypertriglyceridemia, and insulin resistance." (PMID 36837811, 2023). "The critical roles that the phosphatase cascade plays in humans and mice are typified by assorted lipinopathies (e.g., lipodystrophy, insulin resistance, peripheral neuropathy, rhabdomyolysis) that result by loss of lipin 1 PA phosphatase function." (PMID 37030502, 2023). "The mutations in Lpin1 resulted in systemic insulin resistance, and downregulation of Lpin1 in C2C12 myotubes via siRNA transfection suppressed insulin action due to the elevated accumulation of intermediate ceramide." (PMID 31338039, 2019). "Lpin1 gene was originally identified as the deficient gene causing lipodystrophy, insulin resistance, peripheral neuropathy and neonatal fatty liver in the fld (also known as Lpin1) mouse model." (PMID 27344312, 2016). "In this regard, it is interesting to note that loss of function mutations in LPAAT-β and Lipin 1 both result in lipodystrophy and insulin resistance." (PMID 24205284, 2013). "Mutations in the Lpin1 gene lead to fatty liver dystrophy (fld) in fld mice, characterized by loss of body fat, fatty liver, hypertriglyceridemia, and insulin resistance." (PMID 19936100, 2008). "Phosphatidate phosphatase LPIN1 plays an important role in adipocyte differentiation and lipid metabolism; decreased Lpin1 expression is correlated with insulin resistance, and mutations in Lpin1 determine cognitive impairment in mice with fatty liver dystrophy." (PMID 35875664, 2022). "The analysis of pathway-specific methylation changes in three tissue types revealed that the LPIN1 gene correlated with multi-tissue insulin resistance." (PMID 40981068, 2025). "Herein we found that adipose tissue LPIN1 expression is decreased in people with obesity compared with lean subjects, and low LPIN1 expression correlated with multi-tissue insulin resistance and increased rates of hepatic de novo lipogenesis." (PMID 39405118, 2024). "Although Adn-Lpin1–/– mice were lean, they showed features of insulin resistance and steatosis observed in our participants with obesity." (PMID 39405118, 2024). "Huang S., Huang S., Wang X., Zhang Q., Liu J., Leng Y. Downregulationof lipin-1 induces insulin resistance by increasing intracellularceramide accumulation in C2C12 myotubes." (PMID 38465251, 2024). "These mice also exhibited insulin resistance despite being lean, whereas lipin 1–overexpressing mice had increased adiposity yet were insulin sensitive." (PMID 39405118, 2024).
Insulin resistance (continued). "Activation of PKC isoforms by DAG accumulation in insulin-sensitive tissues has been linked to insulin resistance in obesity, and in mouse liver, lipin 1 mediated DAG production led to insulin resistance via activation of PKCε." (PMID 33003344, 2020). "Genetic knockdown of lipin 1 in mice induces lipodystrophy and insulin resistance and alters hepatic metabolism, whereas transgenic mice overexpressing lipin 1 show an obese phenotype." (PMID 31277421, 2019). "In our cohort, adipose tissue expression confirmed that lipin-1 is altered in type 2 diabetes and that LPIN1 is negatively associated with insulin resistance." (PMID 27344312, 2016). "Acute adenoviral-mediated knockdown of lipin 1 or lipin 2 was shown to reduce hepatic DAG, PKCε activation, and associated insulin resistance." (PMID 26273583, 2015). "Lipin 1 belongs to a novel family of nuclear proteins that are involved in adipose tissue development and insulin resistance." (PMID 19936100, 2008). "Because insulin resistance and liver disease progression are highly related, we confirmed the increased expression of several markers of metabolically associated steatohepatitis (MASH) development in Adn-Lpin1–/– mice by quantitative reverse transcriptase PCR." (PMID 39405118, 2024). "While fld mice manifested lipodystrophy and insulin resistance, specific overexpression of lipin 1 in adipose tissue promoted insulin sensitivity and a drop in blood glucose despite increased adiposity, indicating lipin’s role in regulating systemic metabolism via adipose tissue." (PMID 37964368, 2023). "However, other work in hepatocytes has suggested that PA induces insulin resistance by suppressing mTORC2 and that lipin 1 overexpression actually attenuated insulin resistance." (PMID 33003344, 2020). "Among them, Lpin1 has been reported to play an important role in liver lipid metabolism and insulin resistance, Furthermore, Lpin1 protein decreased in Mettl3Ctrl(HFD) mouse liver (compared with Mettl3Ctrl(ND)) while increased in Mettl3cKO(HFD) mouse liver (compared with Mettl3Ctrl(HFD))." (PMID 33160098, 2020). "In our data, significantly upregulated Lpin1 indicated that insulin resistance might be improved in skeletal muscle of exercise GK rats." (PMID 31338039, 2019). "Notably, although significant dyslipidemia was observed in fld mice, human patients with LPIN1 mutations appeared to have a normal lipid spectrum and did not exhibit insulin resistance or liver steatosis." (PMID 37964368, 2023). "Thus, the role of lipin 1 in hepatic insulin resistance remains controversial." (PMID 33003344, 2020). "Although loss of lipin-1 in mouse models leads to manifest lipodystrophy, hepatic steatosis, and insulin resistance, so far none of these pathological conditions have also been observed in human individuals deficient in lipin-1, who have normal adipose tissue distribution and fat weight." (PMID 28986436, 2017). "Given the established role of SIRT1 in mitochondrial biogenesis and the involvement of PPARγ/Lipin-1 in lipid handling, this pathway may contribute to the balance between lipid storage and oxidation, with potential implications for obesity, dyslipidemia, and insulin resistance." (PMID 41007632, 2025). "Indeed, lipin 1 is a negative regulator of inflammatory cytokine secretion, and it exerts its effects by directly repressing NFATc4, while inhibition of lipin 1 expression increases chemotactic protein-1 expression in monocytes, as well as adipose inflammation and systemic insulin resistance." (PMID 37964368, 2023). "Among these DMRs, SREBF1, HOXA5, CPT1A, LPIN1, and PHGDH have established roles in adipose tissue biology and insulin resistance." (PMID 33243154, 2020). "Mechanistically, activation of lipin 1 can increase cellular DAG; thereby activating PKCε and driving insulin resistance." (PMID 33003344, 2020).
Insulin resistance (continued). "We found that LPIN1 expression correlates with measures of skeletal muscle and hepatic insulin sensitivity and inversely correlates with hepatic de novo lipogenesis (DNL), a sensitive marker of hepatic insulin resistance and a characteristic of MASLD." (PMID 39405118, 2024). "Lipin 1 expression in adipose tissue displayed a negative association with BMI, insulin resistance, serum TAG, and leptin levels, indicating a possible relationship between adequate level of adipose lipin 1 and advantages in glucose and fatty acid disposal." (PMID 37964368, 2023). "A strong negative correlation between lipin 1 mRNA levels in adipose tissue and glucose levels, insulin levels, and insulin resistance has been described in mice and humans." (PMID 26086818, 2015). "Similarly, we have recently found that liver-specific lipin 1 knockout mice are not protected from hepatic steatosis and insulin resistance after high fat diet (our unpublished results)." (PMID 26273583, 2015).
Obesity (27 papers, 2014 to 2026). Accumulation of substantial excess body fat. "Conversely, LPIN1 overexpression in adipose tissuesor skeletal muscles causes obesity in transgenic mice (Phan,Reue, 2005)." (PMID 38465251, 2024). "LPIN1 was first found in fatty liver dystrophy mice, and the mutation of LPIN1 can lead to fat malnutrition in fatty liver dystrophy mice, while overexpression of LPIN1 can lead to obesity in mice." (PMID 36672909, 2023). "Though first observed in mouse adipocytes, this effect on PKA activity is also observed in lipin 1-deficient mouse liver and heart and lipin 1 abundance in adipose tissue of humans with obesity is inversely correlated with basal lipolytic rates." (PMID 33003344, 2020). "High expression of Lpin1 in adipose tissue and skeletal muscle can cause obesity, but the insulin sensitivity is different in the two tissues." (PMID 30902099, 2019). "In contrast to the effects of lipin-1 deficiency, selective overexpression of lipin-1 mRNA levels in adipocytes induced obesity in transgenic mice, with increased size and triglyceride content in adipocytes." (PMID 31133852, 2019). "Spontaneous mutations in the LIPIN1 gene in mammals, which cause impaired lipin-1 function, contribute to common metabolic dysregulation and several major diseases, such as obesity, hyperinsulinemia, type 2 diabetes, fatty liver distrophy and hypertension." (PMID 24586157, 2014). "Obesity-associated microenvironmental factors and other Src-activating growth factors, including the epidermal growth factor, activate Src and promote Src-mediated lipin-1 phosphorylation on Tyr398, Tyr413 and Tyr795 residues." (PMID 33203880, 2020). "Importantly, it was estimated that 40-70% of genetic factors that are related to cancer development were found to be strongly associated with obesity, including those involved in lipid metabolism, such as LPIN1, hormone-sensitive lipase LIPE and fatty acid synthase FASN12,38,39." (PMID 33203880, 2020). "The available research shows that LPIN1 gene methylation is decreased in people with obesity, compared to lean individuals." (PMID 40981068, 2025). "Herein, we have shown that adipocyte LPIN1 expression is reduced in people with obesity compared with people who are lean." (PMID 39405118, 2024). "A recent study showed that LPIN1 expression was diminished in individuals with metabolically unhealthy obesity and that it correlated not only with insulin sensitivity but also with hepatic lipogenesis." (PMID 37964368, 2023). "In vivo, conditions such as obesity and fasting promote glucocorticoid levels and also contribute to elevated levels of lipin 1 mRNA in adipose tissue." (PMID 37964368, 2023). "Fat-specific lipin 1 knockout mice have somewhat smaller fat pads on a standard diet, but a high fat diet produces a robust phenotype and fat-specific lipin 1 knockouts are highly resistant to diet-induced obesity." (PMID 33003344, 2020). "Recently, endoplasmic reticulum stress has been shown to be involved in the pathogenesis of obesity through suppression of the Lipin-1 expression in 3T3-L1 adipocytes." (PMID 29534036, 2018). "Due to its effects on hepatic oxidative capacity, circulating TG and free fatty acid levels, LPIN-1 has been suggested as a potential therapeutic target for obesity-related dyslipidaemia and NAFLD." (PMID 28096887, 2017). "At the protein level, SAT showed only lipin-1 was downregulated in obesity and in type 2 diabetes compared with normoweight (p = 0.034)." (PMID 27344312, 2016). "Additionally, E2 downregulates the Lipin 1 (LPIN1) gene, which is involved in lipide metabolism and can promote obesity when overexpressed." (PMID 40278371, 2025). "Previous studies have used a conditional allele to knock out Lpin1 in adult adipocytes, but this was done in lean chow-fed mice without obesity." (PMID 39405118, 2024).
Obesity (continued). "Exactly how and when adipose tissue Lpin1 expression declines in obesity remains controversial, as studies have reported both increased and decreased adipose tissue lipin 1 mRNA in obesity, which may be dependent on diet/genetic model and duration of obesity." (PMID 39405118, 2024). "Interference with LPIN1 inhibited adipose tissue development and significantly reduced adipose tissue quality, whereas overexpression of LPIN1 in skeletal muscle or adipose tissue promoted obesity in mice." (PMID 37048451, 2023). "However, not all obese mouse models exhibit an induction in lipin 1 and lipin 1 seems to be decreased in human subjects with obesity and hepatic steatosis." (PMID 33003344, 2020). "Conversely, overexpression of Lipin 1 accelerates adipocyte differentiation and leads to obesity." (PMID 32475074, 2020). "In many models of obesity-related related fatty liver disease, lipin 1 expression is increased." (PMID 33003344, 2020). "Although some cytokines such as TNFα and IL1β reduce adipose Lipin-1 expression, the mechanism by which the expression of Lipin-1 was impaired in adipose tissue in obesity states remains unclear." (PMID 29534036, 2018). "Underscoring the importance of lipins in this latter process, mutation of mouse lipin-1 causes a near complete absence of TAGs in white adipose tissue and defects in adipocyte differentiation, both common signs of lipodystrophy, while overexpression of mouse lipin-1 promotes obesity." (PMID 25117580, 2014). "Other genes within the magenta module play a role in metabolic functions and obesity including genes that code for lipase (LIPA), phospholipid transfer protein (PTLP), and lipid metabolism (e.g., LPIN1)." (PMID 32151267, 2020). "Several of these genes, like LEP, PPARA, PPARD, LPIN1, SREBP1, and ADIPOQ are described in obesity in both humans and mice." (PMID 31921306, 2019). "LPIN1 expression was reduced in both SAT (p < 0.001) and VAT (p = 0.021) in the obesity and type 2 diabetes groups compared with normoweight." (PMID 27344312, 2016). "Subsequently, the balance between TAG anabolism and catabolism may be impaired through the regulation of lipin 1 phosphatidic acid phosphohydrolase enzyme activity and the lipin 1-PPARα-PGC1α pathway, further leading to HTG, NAFLD, and obesity." (PMID 37964368, 2023). "Furthermore, in a genetic model of obesity, the UCP-DTA mouse, lipin 1 expression was decreased and lipin 1 overexpression improved insulin signaling and glucose tolerance." (PMID 33003344, 2020).